IL7 (interleukin 7)
Diseases named in the same sentence as IL7 in open-access papers (continued):
Sharing a sentence is not in itself a finding about the gene and the disease.
COVID-19 (continued). "A selected set of systemic mediators (IL-6, IFN-γ, IL-1Ra, IL-13, PDGF and IL-7) were identified as putative laboratory markers, applicable as complementary records for the clinical management of patients with severe COVID-19." (PMID 36451835, 2022). "In COVID-19, the role of IL-7 is usually investigated through the prism of additional assessment of cellular responses (CD4+ and CD8+ lymphocytes)." (PMID 36430621, 2022). "COVID-19 patients have high levels of pro-inflammatory cytokines and chemokines such as IL-1β, IL-2, IL-6, IL-7, IL-10, IFN-γ, TNF-α, G-CSF, CCL2, and CXCL10." (PMID 35782361, 2022). "Another host-oriented strategy in evaluation for COVID-19 is the possibility to use IL-7 to support the host’s immune system." (PMID 36558048, 2022). "Third, a board range of cytokines induced in patients with severe COVID-19, including IL-2, IL-7 and IL-6 family cytokines, employ JAK1 for signal transduction." (PMID 35317858, 2022). "IL-7 substitution is a potential treatment to restore lymphocyte count and function and reduce mortality in severe COVID-19." (PMID 35625671, 2022). "The COVID-19 group had significantly higher plasma levels of IL-1β, IL-4, IL-7, IL-8, IL-12, TNF, IP-10, eotaxin, GM-CSF, bFGF, and the complement activation products TCC and C3bc, as compared to the non-COVID-19 group." (PMID 35222429, 2022). "High levels of proinflammatory cytokines, such as IL-1, IL-6, IL-7, IL-12, IFN-γ, TNF-α, IP-10, MIP-1A, MCP-1, GCSF, and IP-10, have been observed in COVID-19 patients and are generally associated with severe lung damage." (PMID 34463916, 2022). "Data analysis demonstrated an increased order of magnitude (≥3x) for CXCL8, CCL3, IL-6, IFN-γ, G-CSF and decreased order of magnitude (≤0.3x) for CCL11, IL-4, IL-5, IL-10, PDGF and IL-7 in COVID-19 patients throughout the kinetic follow-up." (PMID 36451835, 2022). "Specifically, ncfDNA was correlated with cytokines/chemokines such as IL-15, IL-8, Eotaxin-3, IL-1β, IL-10, IL-16, VEGF, IL-6, IL-7, GM-CSF and IL-1α in SOTRs with COVID-19." (PMID 35075453, 2022). "COVID-19 patients show higher concentrations of IL-2, IL-7, IL-10, G-CSF, IP10 (CXCL10), MCP-1 (CCL2), MIP1a (CCL3) and TNF-α than non-COVID-19 patients." (PMID 35901034, 2022). "COVID-19 is characterized by high levels of pro-inflammatory cytokines and chemokines, including IL-2, IL-7, IL-10, G-CSF, IP10, MIP-1A, MCP-1, and TNFα, especially in patients cared for in ICU." (PMID 36423162, 2022). "Among COVID-19 patients, the most common disorders of cytokines and chemokines are increased levels of IL-1β, IL-2, IL-6, interleukin-7 (IL-7), IL-10, TNF-α, CRP, chemokine ligand 2 (CCL2), as well as an increase or decrease in the concentration of IFN-γ." (PMID 36294388, 2022). "Meanwhile, elevated levels of serum IL-2, TNF-α, IL-7, granulocyte colony-stimulating factor, and interferon-gamma-induced protein 10 were correlated with the severity of COVID-19." (PMID 36299906, 2022). "In contrast, COVID-19 featured higher IL-5, IL-7, IL-17A, CXCL8, and VEGF; CXCL8 was three-fold higher in COVID than in MAS, and VEGF is absent in MAS-induced cytokine storms." (PMID 35401519, 2022). "Impressively, IL-7 at 10 μg/kg was well-tolerated, resulting in increased lymphocyte count, and subsequently improved clinical outcomes in COVID-19 patients." (PMID 35284964, 2022). "IL-7 immunotherapy is currently being evaluated as a treatment to reverse the lymphopenia in COVID-19 patients and was shown to restore lymphocyte count in critically ill COVID-19 patients without worsening pulmonary injury and inflammation." (PMID 34238985, 2021). "In the COVID-19 placentas, some studies observed elevated IL-5 levels as well as decreased IL-7 and TNF-related apoptosis-inducing ligand levels." (PMID 35071136, 2021).
COVID-19 (continued). "The progress of COVID-19 from mild illness to severe form depends on the circulatory levels of inflammatory cytokines and chemokines such as IL-7, IL-8, IL-9, IL-10, GCSF, GMCSF, TNFα, and VEGFA." (PMID 34786427, 2021). "In a recent case series, 12 critically ill patients with COVID-19 and severe lymphopenia were treated with IL-7 therapy." (PMID 34925323, 2021). "Patients with cardiovascular failure and hypotension requiring intravenous pressors showed lower IL-7 levels later in their COVID-19 trajectory, while CXCL5, IL-12, and ANGPT-1 levels were depressed early during the course of infection." (PMID 34177897, 2021). "In contrast, COVID-19 was distinguished by a lymphocyte T cytokine response, as reflected by an increase in IL-2, IL-4, IL-5, IL-7, IL-13, IL-17, and soluble CD40L (sCD40L)." (PMID 35111777, 2021). "In COVID-19 patients, the pro-inflammatory cytokines like IL-1, IL-2, IL-6, IL-7, IL-10, IP-10, and TNFα as well as chemokines like IL-8 are found in higher concentrations." (PMID 33981235, 2021). "Severely ill patients hospitalised with COVID-19 exhibit increased levels of Interleukin (IL)-1β, IL-2, IL-6, IL-7, IL-8, IL-10, IL-17, granulocyte colony stimulating factor (G-CSF), monocyte chemoattractant protein 1 (MCP-1) and tumor necrosis factor (TNF)." (PMID 34205262, 2021). "To attempt to rescue the cytotoxic function of MAIT cells in COVID-19 patients, we treated PBMCs with IL-7 for 24 h." (PMID 34238985, 2021). "Serum levels of IL-7, IL-10 and IP-10 were elevated in COVID-19 asymptomatic cases compared to healthy controls, whereas IL-1RΑ, IL-1β, IL-6 and IP-10 were higher in symptomatic compared to asymptomatic COVID-19 patients." (PMID 34603318, 2021). "Other cytokines similarly increased in patients with severe pandemic influenza A(H1N1) and COVID-19 included IL-7, IL-15, IL8, and CXCL10." (PMID 33995342, 2021). "Previous studies have found an association between an increase in levels of IL-2, IL-6, IL-7, IL-10 and TNF-α and the severity or mortality of COVID-19." (PMID 34490065, 2021). "Of note, concentrations of circulating IL-7 and IFNγ, which are increased in severe COVID-19, are similar in men and women." (PMID 34434199, 2021). "IL-7 also significantly increased the frequency of IFN-γ expressing cells in COVID-19 patients but to a lower level than that achieved by IL-12/IL-18 stimulation." (PMID 34238985, 2021). "The supportive role of IL-7 in lymphocyte survival and expansion provides clinical implications for the recovery of function of lymphocytes in severe/critical COVID-19." (PMID 34234112, 2021). "As another example, monitoring of COVID-19-associated CRS patient cytokine profiles in 2019 revealed higher levels of IL-2, IL-7, IL-10, G-SCF, MCP-1, MIP-1α, and TNF-α in plasma of intensive care unit (ICU) patients versus plasma of non-ICU patients." (PMID 34884813, 2021). "In contrast, a small albeit statistically significant increase in IL-7 levels was noted in patients with critical COVID-19." (PMID 33232303, 2021). "In severely sick COVID-19 patients, cytokine storm syndrome was examined, and it was reported that the extent of interleukins (IL-2, IL-7, IL-10) was high in fundamentally sick patients." (PMID 33907373, 2021). "Here, we propose that IL-7 has many potential applications in COVID-19, as a biomarker, as a therapeutic agent, and as a vaccine adjuvant." (PMID 34603318, 2021). "In fact, patients with COVID-19 display a pro-inflammatory (IL-1β, IL-6, IL-7, IL-8, IL-9, FGF, G-CSF, GM-CSF, IFN-ɣ, CXCL10, CCL2, CCL3, CCL4, PDGF, TNFα, and VEGF) and regulatory cytokine profile (IL-10 and TGFβ; cytokine storm)." (PMID 33995342, 2021). "IL-4, IL-7, IL-8, IL-12p70, IL-15, and VEGF were also associated with increased risk of intubation in COVID-19 subjects." (PMID 33995342, 2021).
COVID-19 (continued). "Meanwhile, increased serum levels of IL-2, TNF-α, IL-7, granulocyte-colony stimulating factor and interferon-γ inducible protein 10 (CXCL10) are associated with COVID-19 disease severity." (PMID 33581688, 2021). "Among COVID-19 patients levels of IL-7, IP-10 and G-CSF were higher in male and MDC level was increased in female." (PMID 34858428, 2021). "Encouragingly, IL-7 therapy also proved effective for novel coronavirus disease (COVID-19), which represents the greatest medical challenge in decades." (PMID 34925323, 2021). "These cytokines, such as IL-6, IL-7, CCL-2/MCP-1, CCL-3/CCL-4 MIP-1α/β, TNF-α, and G-CSF, have been implicated in COVID-19 pathogenesis." (PMID 34341347, 2021). "In this study, we focus on the effect of SARS-CoV-2 infection on the frequency, activity and phenotype of MAIT cells and investigate the capacity of IL-7 to enhance the function of MAIT cells in patients with COVID-19 in vitro." (PMID 34238985, 2021). "It was recently reported that in patients with severe COVID-19 the levels of IL-2, IL-7, IL-10, GSCF, IP10, MCP-1, MIP1A, and TNF-α are dramatically elevated." (PMID 34361736, 2021). "Typically, the critical COVID-19 patients reported with higher plasma concentrations of IL-7, IL-8, IL-9, basic fibroblast growth factor, granulocyte colony-stimulating factor and granulocyte-macrophage colony-stimulating factor were in high fatality." (PMID 33604601, 2021). "Critical COVID-19 is distinguished by very high levels of IL-1β and T lymphocyte activation (including IL-7), whereas septic shock displays higher levels of IL-6, IL-8 and a more significant myeloid response (including TREM-1 and IL-1ra)." (PMID 35111777, 2021). "Multicenter clinical trials are recruiting study participants to understand the clinical and immunological benefits of IL-7 treatment in COVID-19 patients (NCT04379076, NCT04407689, NCT04426201, NCT04442178, NCT04927169)." (PMID 34603318, 2021). "As mentioned, future studies should highlight the clinical, immunological and virological outcomes of IL-7 therapy in COVID-19 patients." (PMID 34603318, 2021). "Here, we discuss the critical function of IL-7 in diagnosis, prognosis and treatment of COVID-19 patients." (PMID 34603318, 2021). "In a study with COVID-19 patients, elevated serum IL-7 levels were measured in symptomatic and asymptomatic patients compared to healthy controls and convalescent patients." (PMID 34603318, 2021). "IL-7 treatment raised the frequency of perforin expressing MAIT cells from COVID-19 patients to a level comparable to the IL-12/18 stimulated control groups." (PMID 34238985, 2021). "Since lymphopenia and lymphocyte exhaustion are hallmarks of COVID-19, IL-7—the major cytokine promoting lymphocyte expansion and possibly reversal of T cell exhaustion is considered to be restoring immune system homeostasis." (PMID 32733487, 2020). "Patients with a severe COVID-19 condition, on the other hand, have an increased IL-7 production, but contradictorily they also have severe lymphopenia." (PMID 33193331, 2020). "A study indicated that COVID-19 patients treated in the intensive care unit with severe clinical features had a high level of innate cytokines IL-2, IL-10, IL-7, TNF-α, chemokines IP-10, MCP-1, and MIP-1A." (PMID 33101440, 2020). "The mean number of IFN-ɣ–producing T cells from COVID-19 patients nearly doubled, from 101 ± 21 to 201 ± 36 (P < 0.0001), following ex vivo administration of IL-7." (PMID 32687484, 2020). "Several of these agents (NKG2D-ACE2 CAR-NK cells, anti–PD-1, IL-7) are either in active clinical trials or in the planning stages for COVID-19 (NCT04324996, NCT04356508, NCT04379076, respectively)." (PMID 32687484, 2020). "While suppression of this pro-inflammatory cytokine storm is considered essential to combat COVID-19, some cytokines such as Type-I interferon and IL-7 have been found to be beneficial." (PMID 32733487, 2020).
COVID-19 (continued). "To test the potential efficacy for IL-7 as an immunoadjuvant therapy to restore COVID-19–induced T cell exhaustion, we cocultured patient-derived PBMCs with IL-7 for ELISpot analysis." (PMID 32687484, 2020). "Of particular relevance regarding potential immune adjuvant therapy for COVID-19 are the ELISpot results showing that ex vivo IL-7 increased IFN-ɣ production of stimulated T cells nearly 2-fold." (PMID 32687484, 2020). "Administration of IL-7 alone or in combination with other therapies warrants serious consideration for patients with COVID-19 and evidence of immunosuppression." (PMID 32697322, 2020). "Although we cannot draw any definitive conclusion about a single case report, the present results show IL-7 beneficial effects in improving immune functions in a COVID-19 patient." (PMID 32728202, 2020). "In contrast, pro-inflammatory cytokines and chemokines, including CCL14, CCL23, IL7, IL16 and IL18, were preferentially expressed in men, underlying the higher susceptibility of men developing cytokine release syndrome in COVID-19." (PMID 32974111, 2020). "Higher plasma levels of cytokines, including interleukin (IL)-6, IL-2, IL-7, IL-10, and tumor necrosis factor-α, were found in patients with COVID-19, which implies the occurrence of a cytokine storm and its association with disease severity." (PMID 33335906, 2020). "For instance, in plasma of COVID-19 patients, high concentrations of IL-2, IL-6, and IL-7 were observed." (PMID 33206688, 2020). "IL-7 reverses T cell exhaustion in COVID-19 and should be considered as a potential therapy in this highly lethal disorder." (PMID 32687484, 2020). "Therefore, this significant decrease in TEAEs is consistent with a putative beneficial effect of IL-7 in patients with COVID-19." (PMID 39903535, 2025). "Further analysis showed an overall lower correlation between the cytokines IL-2R, IL-6, IL-7, IL-8, and IL-10 and metabolic phenotype 3 among non-survivors, indicating a lower association of these cytokines with COVID-19-related metabolites." (PMID 41002992, 2025). "Conversely, reduced IL-7 receptor expression in neutrophils and lower IL-7 levels in the plasma of COVID-19 patients could possibly impact B cell development." (PMID 39012145, 2024). "Among them, serum levels of IL-10RB, FGF-19, and CCL-2 positively contributed to both hospitalized and critical COVID-19 conditions (OR: 1.10~1.16), while the other 4 proteins conferred risk on critical COVID-19 only (OR: 1.07~1.16), including EIF4EBP1, IL-7, NTF3, and LIF." (PMID 38455043, 2024). "Likewise, a significant reduction in IL-7 levels in the plasma of COVID-19 patients either admitted to the ICU or ward compared with HCs was noted." (PMID 39012145, 2024). "The mediators CCL3, CCL4, CCL2, CCL5, IL-12, IL-15, IL-1Ra, and PDGF were higher in healthy volunteers, while the mediators CCL11, CXCL10, IL-1b, IL-6, TNF-a, IFN-g, IL-17, IL-9, IL-10, IL-13, FGF-basic, G-CSF, GM-CSF, IL-7, and IL-2 were increased in COVID-19 positive patients." (PMID 37903875, 2023). "Reduced IL-7 after COVID-19 could reflect persistent lymphocyte exhaustion, contributing to inefficient viral clearance and chronic immune stimulation." (PMID 36844209, 2023). "Contrarily, patients with COVID-19 who were severely infected experienced an excessive release of cytokines and chemokines, such as interleukin (IL)-1, IL-2, IL-6, IL-7, IL-8, IL-10, granulocyte-colony stimulating factor (GCSF), and tumour necrosis factor-alpha (TNF-α)." (PMID 36679947, 2023). "Furthermore, in the KEGG pathway analysis four pathways were identified, including neuroactive ligand-receptor interaction, IL-7 signaling pathway, coronavirus disease-COVID-19, and rheumatoid arthritis." (PMID 36824434, 2023).
COVID-19 (continued). "Additional studies have also revealed that patients with severe COVID-19 have a significantly elevated cytokine profile of IL-2, IL-6, IL-7, IL-10, IP-10, MCP-1, TNF-α, macrophage inflammatory protein 1 alpha, and granulocyte-CSF compared to patients with mild to moderate COVID-19." (PMID 37457959, 2023). "Hence, considering the plethora of advantages of IL-7, many clinical trials have been registered to uncover the effectiveness of recombinant IL7 in restoring lymphocyte counts in patients with COVID-19." (PMID 36679947, 2023). "Furthermore, as compared to healthy controls and mild/moderate COVID-19 patients, plasma IL-7 levels were considerably higher in severe COVID-19 patients in this study." (PMID 35958594, 2022). "Recent studies on COVID-19 suggest that cytokine release syndrome is associated with the severity of disease; this syndrome is characterized by increased TNF-α, interleukin (IL)-6, IL-2, IL-7, and IL-10." (PMID 36361745, 2022). "However, in univariate analysis, the cytokines TGF-β, CXCL-10, IFN gamma, and IL-7 significantly affected mortality in COVID-19 patients." (PMID 36286038, 2022). "However, in a univariate analysis, TGF-β, CXCL-10, IFN gamma, and IL-7 affected mortality in COVID-19 patients." (PMID 36286038, 2022). "Moreover, severe COVID-19 patients requiring intensive care in the hospital have high plasma IL-2, IL-7, IL-10, and TNF-α levels." (PMID 36035409, 2022). "An investigation found a higher expression of IL-16, IL-7, ILCs, and IL-18 in males with COVID-19 than in females, which may promote COVID-19-related cytokine storms." (PMID 35664675, 2022). "COVID-19 respiratory distress begins with an early inflammation so that pulmonary compliance is reduced by activation of intercellular inflammatory pathways, cytokine synthesis, or storm (excessive release of IL-2, IL-6, IL-7, IL-8, IL10, and TNF-α)." (PMID 35656183, 2022). "In particular, adults with severe acute COVID-19 inflammation had higher levels of IL-7 and IL-8 than pediatric patients with KD and MIS-C, while IL-17A and endothelial and smooth muscle cell-derived neuropilin-like (ESDN) were higher in patients with KD than in patients with MIS-C." (PMID 35558368, 2022). "Pneumonia is linked to blood levels of IL-1β, IL-7, IL-8, IL-9, and IL1-5 in COVID-19." (PMID 36111104, 2022). "Besides IL-6, patients with severe cases of COVID-19 have higher plasma levels of other elements of cytokine storms, including IL-2, IL-7, IL-8, IL-10, and tumor necrosis factor-α (TNF-α)." (PMID 35295802, 2022). "Among elevated plasma inflammatory mediator levels; CRP, ICAM-1, SAA, VCAM-1, CXCL10, IL-7, IL-10 and Flt-1 may suggest the severity of COVID-19." (PMID 35958594, 2022). "Moreover, a selected set of serum soluble mediators (IL-6, IFN-γ, IL-1Ra, IL-13, PDGF and IL-7) were pointed out as promising biomarkers for the clinical management of severe COVID-19 patients." (PMID 36451835, 2022). "A decrease in CD127 expression in severe COVID-19 patients may be a significant factor in IL-7 treatment." (PMID 35625671, 2022). "Overall, these results demonstrate the ability of a selected set of systemic mediators (IL-6, IFN-γ, IL-1Ra, IL-13, PDGF and IL-7) as putative laboratory markers that are applicable as complementary records in the clinical management of severe COVID-19 patients." (PMID 36451835, 2022). "Furthermore, IL-1Ra, IL-13, PDGF and IL-7 were also identified as promising molecules to distinguish COVID-19 patients progressing to a worse prognosis (MV or Death)." (PMID 36451835, 2022). "Considering the protective role of IL-7, we can speculate that the increase of IL-7 may be a feedback mechanism in response to the lymphopenia in patients with severe/critical COVID-19." (PMID 34234112, 2021).